PRKAG2 (protein kinase AMP-activated non-catalytic subunit gamma 2)
Diseases named in the same sentence as PRKAG2 in open-access papers (continued):
Sharing a sentence is not in itself a finding about the gene and the disease.
Danon disease (25 papers, 2012 to 2026). A lysosomal glycogen storage disease characterized by severe cardiomyopathy and variable degrees of muscle weakness, frequently associated with intellectual deficit. "The prognosis of patients with PRKAG2 genetic variants is better than that of patients with Danon disease, especially for men, although it is still poorer compared to those with sarcomeric HCM." (PMID 39273120, 2024). "Mutations in the gene that encodes PRKAG2 have been associated with glycogen storage cardiomyopathies by disrupting AMPK's ability to bind to AMP, dysregulating the metabolic and glucidic uptake, and causing the deposition of amylopectin and glycogen." (PMID 36426223, 2022). "Clinically, PRKAG2 mutations cause glycogen-storage cardiomyopathy, ventricular preexcitation, and conduction system degeneration." (PMID 35360035, 2022). "PRKAG2 is associated with glycogen-storage cardiomyopathy and CTF1 induces cardiac myocyte hypertrophy in vitro." (PMID 30732658, 2019). "Finally, the mutation of PRKAG2 is known to cause the glycogen-storage cardiomyopathy that resembles HCM but is distinguished by electrophysiological abnormalities." (PMID 30813608, 2019). "Promising pre-clinical studies show that glycogen-storage cardiomyopathy and conduction system degeneration associated with PRKAG2 mutation might be reversible, and the development of accessory pathways may be prevented by inhibition of glycogen accumulation during early postnatal development." (PMID 39273120, 2024). "Less frequent genetic causes are linked to infiltrative or metabolic diseases, such as GLA mutations in Fabry disease, TTR in transthyretin amyloidosis, LAMP2 in Danon disease, and PRKAG2 in glycogen storage cardiomyopathy." (PMID 40868441, 2025). "Among GSDs, Pompe disease (GSD type IIa), Danon disease (GSD type IIb), Cori disease (GSD type III), and PRKAG2 disease are particularly notable for their association with HCM that manifests during childhood." (PMID 41463072, 2025). "In contrast, both Danon disease and PRKAG2 disease usually emerge after the first year of life, with Danon disease exhibiting an earlier onset in male patients and presenting with muscle involvement and cognitive impairments." (PMID 41463072, 2025). "Pre-excitation and conduction disease put the focus on LAMP2 (Danon disease), PRKAG2, TTR (amyloidosis) or GLA (Fabry disease)." (PMID 30393635, 2018). "Other diseases which can lead to an HCM phenotype include inflammatory diseases (e.g., sarcoidosis), storage diseases (e.g., Danon disease, hemochromatosis, PRKAG2), syndromal diseases (Friedreich ataxia, FHL‐1, malformation syndromes), mitochondrial diseases and drug-induced cardiomyopathy." (PMID 39352517, 2024). "In addition, it provides a definitive molecular diagnosis and allows the identification of phenocopies (for example Anderson-Fabry disease, TTR amyloidosis, Danon disease, or PRKAG2 cardiac glycogenosis)." (PMID 37048573, 2023). "Shortened PQ interval is observed in some patients with HCM, particularly in those without contractile proteins mutations, such as PRKAG2 mutations, Danon disease, Pompe disease and Fabry disease." (PMID 22912742, 2012). "Nonetheless, the identification of a pathogenic mutation may help the cardiologist make tailored therapeutic choices and distinguish rare mimics such as Fabry disease, Danon disease, amyloidosis caused by TTR mutation, or atypical glycogenosis due to mutations in the PRKAG2 gene." (PMID 37048573, 2023). "A small number of hypertrophic patients exhibit Fabry syndrome (GLA gene), Danon disease (LAMP2 gene), cardiac amyloidosis (TTR gene), Wolff—Parkinson—White syndrome (PRKAG2 gene), and mitochondrial cardiomyopathies." (PMID 37048573, 2023). "Additionally, eight were syndromic patients: four with Noonan syndrome (PTPN11 and biallelic LZTR1), two with Danon disease (LAMP2), two with Carvajal syndrome (DSP), and one with atypical glycogen storage disease (PRKAG2)." (PMID 40642871, 2025).
cardiac hypertrophy (23 papers, 2013 to 2026). "Transgenic and knock-in mice with the H530R PRKAG2 mutation replicated human symptoms of ventricular hypertrophy and glycogen storage, suggesting a causal link to PRKAG2 cardiac syndrome." (PMID 38725755, 2024). "Mutations at this locus are known to cause the PRKAG2 cardiac syndrome, an inherited disease characterized by ventricular pre-excitation, supraventricular arrhythmias, and cardiac hypertrophy." (PMID 39513938, 2024). "In conclusion, molecular screening for PRKAG2 mutations should be considered in patients who exhibit cardiac hypertrophy coexisting with ventricular pre-excitation, especially with familial inheritance." (PMID 36556501, 2022). "In patients who exhibit cardiac hypertrophy coexisting with ventricular pre-excitation, genetic screening for PRKAG2 mutations should be considered." (PMID 36556501, 2022). "Collectively, these results suggested that the p.Val336Leu mutation in the PRKAG2 gene was potentially causative in the present family with cardiac hypertrophy and VPE." (PMID 28546535, 2017). "Molecular screening for PRKAG2 mutations should be considered in patients who exhibit cardiac hypertrophy coexisting with VPE." (PMID 28546535, 2017). "In conclusion, molecular screening for PRKAG2 mutations should be considered in patients who exhibit cardiac hypertrophy coexisting with ventricular pre-excitation." (PMID 28546535, 2017). "Mutations in PRKAG2 have been shown to cause cardiac hypertrophy with associated glycogen deposition, Wolff-Parkinson-White syndrome and conduction abnormalities." (PMID 24037260, 2013). "Mutations in γ2 subunit (PRKAG2) have been associated with a cardiac syndrome including inherited ventricular preexcitation, conduction disorder and hypertrophy mimicking hypertrophic cardiomyopathy." (PMID 23741347, 2013). "In summary, we identified a novel de novo PRKAG2 mutation (K485E) in a young patient with ventricular preexcitation, conduction defect, cardiac hypertrophy and rapid progression of heart failure." (PMID 23741347, 2013). "Notably, this hypertrophic response was prevented by rapamycin, an mTOR inhibitor, suggesting that the Akt/mTOR pathway, rather than glycogen accumulation, plays a dominant role in mediating cardiac hypertrophy associated with the N488I PRKAG2 mutation." (PMID 40860364, 2025). "AMPK associated with the T-tubules may regulate ion transport, contributing perhaps to conductive irregularities that accompany cardiac hypertrophy caused by PRKAG2 mutations." (PMID 24037260, 2013). "PRKAG2 cardiac syndrome is a rare autosomal dominant genetic disorder characterized by ventricular preexcitation, supraventricular arrhythmias, and cardiac hypertrophy due to glycogen accumulation in the myocardium." (PMID 39569283, 2024). "The phenotypes of PRKAG2 cardiac syndrome vary, typically with ventricular pre-excitation and cardiac hypertrophy in adolescence and adulthood, and rarely with fetal- and infantile-onset severe hypertrophic cardiomyopathy." (PMID 39569283, 2024). "The symptoms of the PRKAG2 cardiac syndrome vary, ranging from asymptomatic to a phenotype that includes cardiac hypertrophy, primarily involving the left ventricle, supraventricular tachycardia (WPW), increased risk of heart failure, and sudden cardiac death." (PMID 36426223, 2022). "We also examined genes that are not transcriptionally regulated via PPAR α, but tend to alter in cardiac hypertrophy (PRKAG2 and EP300)." (PMID 35224041, 2022). "Point mutation of Prkag2, the γ2 subunit of AMPK, causes cardiac hypertrophy in a transgenic mouse model, accompanied by dramatically increased phosphorylation of 4EBP1." (PMID 30759120, 2019). "Mutations in genes encoding the γ2 subunit of AMP-activated protein kinase (PRKAG2), α-galactosidase A (GLA), and lysosome-associated membrane protein-2 (LAMP2) can cause profound myocardial hypertrophy in association with electrophysiologic defects." (PMID 23700405, 2013).
cardiac hypertrophy (continued). "A study has suggested that patients from a pedigree carrying the PRKAG2-R302Q mutation all showed left atrial enlargement, but some patients were diagnosed with no or mild ventricular hypertrophy." (PMID 35360035, 2022). "Defects in PRKAG2 are associated with a recently described cardiac syndrome triad consisting of familial ventricular preexcitation (Wolff-Parkinson-White syndrome, WPW), conduction system disease and cardiac hypertrophy mimicking HCM." (PMID 23741347, 2013). "However, according to an earlier study, cardiac hypertrophy has a generally progressive nature in PRKAG2, and thus different patterns of LVH in the same family may represent different stages of the disease." (PMID 26496977, 2015). "Both the PRKAG2 cardiac syndrome and HCM are characterized by cardiac hypertrophy, but myofibrillar disarray is previously considered to be a pathological hallmark of HCM." (PMID 23741347, 2013). "The protein kinase AMP-activated non-catalytic subunit gamma 2 (PRKAG2) cardiac syndrome is an autosomal dominant metabolic heart disease characterized by cardiac hypertrophy and conduction abnormalities." (PMID 31842377, 2019).
glycogen storage disease (16 papers, 2013 to 2026). "Only in rare clinical contexts of PRKAG2-associated syndromes do extracardiac manifestations such as progressive structural myopathy occur in the context of systemic glycogen storage disease, including forms associated with the formation of polyglucosan body storage." (PMID 40757593, 2024). "There are hints, for example, that the alglucosidase-alfa enzyme replacement therapy used for the treatment of patients with Morbus Pompe might also be beneficial for patients with PRKAG2-associated glycogen storage disease." (PMID 36498454, 2022). "For example, mutations in the PRKAG2 gene have been linked to a syndrome characterized by ventricular preexcitation, HCM, and glycogen storage disease." (PMID 40337375, 2025). "Specific genetic mutations, such as those in the PRKAG2 gene, have been linked to familial cases of WPW, particularly when associated with glycogen storage diseases and hypertrophic cardiomyopathy (HCM)." (PMID 40337375, 2025). "Most cases of WPW have been linked to pathogenic variants in PRKAG2 or MYH6, glycogen storage disorders, mitochondrial syndromes, or congenital heart diseases such as septal defects, Ebstein malformation of the tricuspid valve, or HCM." (PMID 33797204, 2021).
hypertrophic cardiomyopathy (15 papers, 2013 to 2026). A condition in which the myocardium is hypertrophied without an obvious cause. "PRKAG2 mutations such as R302Q are associated with familial Wolff-Parkinson-White syndrome and hypertrophic cardiomyopathy, leading to metabolic dysregulation and cardiac dysfunction." (PMID 42039356, 2026). "Clinicians must be aware of the possibility of PRKAG2 variants in complex clinical scenarios associating cardiac arrhythmia, preexcitation syndromes, hypertrophic cardiomyopathy, motor neuron disease, and parkinsonism." (PMID 40757593, 2024). "Clinicians must be aware of the possibility of PRKAG2 variants in complex clinical scenarios associated with cardiac arrhythmia, preexcitation syndromes, hypertrophic cardiomyopathy, MND/ALS, and parkinsonism." (PMID 40757593, 2024). "Here, we report a rare neonatal case of severe hypertrophic cardiomyopathy caused by PRKAG2 cardiac syndrome, presenting with refractory chylous ascites and lymphatic malformations." (PMID 39569283, 2024). "In previous studies, p.Arg531Gln was reported to be a mutation in PRKAG2 associated with lethal hypertrophic cardiomyopathy." (PMID 39569283, 2024). "We present a rare case of severe hypertrophic cardiomyopathy with refractory chylous ascites that eventually identified a pathogenic mutation in the PRKAG2 gene." (PMID 39569283, 2024). "The PRKAG2 variant has been reported in a case with hypertrophic cardiomyopathy." (PMID 41282270, 2025). "Among the deleted genes, two genes have cardiac implications: KCNH2, coding for a cardiac potassium channel involved in long QT syndrome (LQTS) (Perrin, Subbiah, Vandenberg, & Hill, 2008); and PRKAG2, associated with hypertrophic cardiomyopathy, cardiac conduction disease, and sudden death." (PMID 31347270, 2019). "In addition, mutations in PRKAG2 have been identified to be associated with hypertrophic cardiomyopathy." (PMID 30559760, 2018). "PRKAG2-related syndromes are associated with complex cardiac arrhythmia, WPWS, hypertrophic cardiomyopathy, and rarely, polyglucosan storage myopathy." (PMID 40757593, 2024). "Hypertrophic cardiomyopathy is associated with an increased incidence of Wolff-Parkinson-White syndrome; reports have suggested that it could be caused by a mutation in the protein-coding gene PRKAG2, which encodes a subunit of the AMP-activated protein kinase." (PMID 36426223, 2022). "PRKAG2 was found to be common to SBP and DBP in South Asians, and has been previously associated with hypertrophic cardiomyopathy and chronic kidney disease." (PMID 31999706, 2020). "Protein kinase adenosine monophosphate-activated non-catalytic subunit gamma 2 (PRKAG2) cardiac syndrome is a rare genetic disorder characterized by hypertrophic cardiomyopathy and heart rhythm disturbances caused by mutations in the PRKAG2 gene." (PMID 39569283, 2024). "Moreover, the deletion includes the PRKAG2 gene, implicated in a nonsarcomeric form of hypertrophic cardiomyopathy, associated with accessory pathway, short PR, and late evidence of supraventricular and ventricular tachycardia, complete heart block, and sudden death." (PMID 31347270, 2019). "In hypertrophic cardiomyopathy (HCM), MYBPC3, MYH7, PRKAG2, RAF1, and RBM20 were prevalent." (PMID 41341110, 2025).
Fabry disease (13 papers, 2012 to 2026). Fabry disease (FD) is a progressive, inherited, multisystemic lysosomal storage disease characterized by specific neurological, cutaneous, renal, cardiovascular, cochleo-vestibular and cerebrovascular manifestations. "Differential diagnosis must be considered when DD is suspected, depending on the signs and symptoms, such as Fabry disease, PRKAG2, Pompe disease, and others." (PMID 42154863, 2026). "Similar mechanism of LGE has been suggested in Anderson-Fabry disease, with intracellular lipid accumulation, and could also explain LGE in our patients with the progressive stage of PRKAG2." (PMID 26496977, 2015).
type 2 diabetes (8 papers, 2013 to 2026). "Conversely, with similarities to pathologic cardiac states such as type 2 diabetes, these findings provide further information on the role that metabolic therapeutic targets may have in the affected PRKAG2 patients." (PMID 23829931, 2013). "The lack of responsiveness to cardiac insulin stimulation in the PRKAG2 mutant mice, where AMPK activity is dysfunctional, is intriguing where a link between insulin stimulation and AMPK is currently under investigation with regards to type 2 diabetes." (PMID 23829931, 2013).
Arrhythmia (7 papers, 2020 to 2026). Any cardiac rhythm other than the normal sinus rhythm. "Using PAS staining, we also found a large accumulation of glycogen in the proband’s atrial tissue and HL-1 cells overexpressing PRKAG2-R302Q, which may also be a substrate of arrhythmia." (PMID 35360035, 2022).
Wolff-Parkinson-White syndrome (7 papers, 2012 to 2026). A cardiac conduction disorder characterized by an electrocardiographic finding of ventricular pre-excitation, which is a short PR interval and a long QRS interval with a delta wave. "Mutations in the γ2 subunit of AMP-activated protein kinase (PRKAG2) gene are known to cause an energetic disease affecting the myocardium and previous studies have confirmed that they can cause Wolff-Parkinson-White (WPW) syndrome, HCM, ventricular pre-excitation and very few symptoms of myopathy." (PMID 36221081, 2022). "The HCM is associated with an increased incidence of WPW syndrome; reports have suggested that it could be caused by a mutation in the protein-coding gene PRKAG2, which encodes a subunit of the AMP-activated protein kinase (AMPK)." (PMID 36426223, 2022). "In the present study, we studied a Chinese family in which the proband presented with the hypertrophic LVNC and confirmed for the first time that PRKAG2 mutation c.905G>A (p.R302Q), previously proposed to be associated with HCM and WPW syndrome, was associated with LVNC." (PMID 36221081, 2022).
heart failure (6 papers, 2013 to 2025). Inability of the heart to pump blood at an adequate rate to meet tissue metabolic requirements. "Contrastingly, in this cohort, expression of proteins associated with AMPK-encoding genes (PRKAA1, PRKAG1, PRKAA2, PRKAB1, PRKAB2 and PRKAG2) are significantly higher in oHCM patients, compared with other heart failure aetiologies, and expression of ALDOA is significantly down-regulated." (PMID 39200175, 2024). "The p.Glu506Lys mutation initially described in a Turkish family with the PRKAG2 cardiac syndrome, was associated with a progressive HCM leading to heart failure with reduced ejection fraction at ~ 40 years of age34." (PMID 33244021, 2020). "Patient 62 (PRKAG2: c.1589A>G, p.His530Arg; LAMA4: c.241C>T p.Pro81Ser) was 26 years old and had suffered from heart failure for 2 years." (PMID 30165862, 2018). "Patients who present with unexplained LVH, electrophysiological abnormalities, early onset of marked LV dilatation and heart failure without elevations of serum CK and ALT should be suspected of PRKAG2 cardiac syndrome." (PMID 23741347, 2013).
PRKAG2 syndrome (6 papers, 2020 to 2025). "Comprehensive genetic testing, including PRKAG2 mutation analysis, is crucial for differentiating PRKAG2 syndrome from sarcomeric HCM and other metabolic cardiomyopathies, ensuring appropriate risk stratification and early intervention." (PMID 40671717, 2025). "Several mutations have been identified to cause PRKAG2 syndrome, and all these have been missense mutations in the PRKAG2 gene." (PMID 36556501, 2022). "PRKAG2 syndrome is an autosomal dominant disorder first mapped to the locus 7q36 in 1991, with the responsible gene identified in 2001.3,6,7 The syndrome results from mutations in PRKAG2, which encodes the γ2 regulatory subunit of adenosine monophosphate-activated protein kinase (AMPK)." (PMID 40671717, 2025). "Mutations in the PRKAG2 gene encoding the 5′ Adenosine Monophosphate-Activated Protein Kinase (AMPK), specifically in its γ2 regulatory subunit, lead to Glycogen storage disease of heart, fetal congenital disorder (PRKAG2 syndrome)." (PMID 33509202, 2021).
atrial fibrillation (5 papers, 2013 to 2025). A disorder characterized by an electrocardiographic finding of a supraventricular arrhythmia characterized by the replacement of consistent P waves by rapid oscillations or fibrillatory waves that vary in size, shape and timing and are accompanied by an irregular ventricular response. "Recently, a high incidence of atrial fibrillation was reported for patients with the PRKAG2-R302Q mutation." (PMID 35360035, 2022). "Even more recently, studies have identified missense mutations in the PRKAG2 gene in some cases of familial WPW especially associated with an early onset of atrial fibrillation and conduction disease." (PMID 23329875, 2013). "Although patients with the PRKAG2-R302Q mutation have a high incidence of atrial fibrillation (AF), the molecular mechanism contributing to the disease remains unclear." (PMID 35360035, 2022).